INS (insulin)
Diseases named in the same sentence as INS in open-access papers (continued):
Sharing a sentence is not in itself a finding about the gene and the disease.
diabetes (continued). "The non-significant relationship between severe hypoglycaemia and MACE was maintained after adjustment for the following baseline characteristics: age, sex, HbA1c, BMI, diabetes duration, insulin regimen, hepatic impairment, renal status and cardiovascular risk group inclusion criteria." (PMID 28913543, 2018). "Additionally, patients are interested in apps embedded with educational information on problem solving techniques, use of insulin pump therapy, signs of diabetes complication and prevention as well as transitioning from paediatric into adult care." (PMID 30532235, 2018). "Fatty acids and leucine, which are both early markers of diabetes, induce acetyl-CoA accumulation and protein acetylation, suggesting that acetylation could be an early event in insulin resistance development." (PMID 29946550, 2018). "Among the miRNAs that play role in insulin signaling, the islet-specific miR-375 and miR-9 have been demonstrated as mechanistic regulators of insulin secretion and play critical roles in glucose homeostasis and the pathogenesis diabetes." (PMID 29373500, 2018). "Others53 have similarly reported a positive association between diabetes distress and insulin use rather than depression in Turkey and China30, suggesting the relationships are consistent across cultures." (PMID 29777153, 2018). "Those with persistent diabetes could mostly reduce their insulin doses by >50%, or decrease the number of oral antidiabetic drugs, while still maintaining improved glycemic control." (PMID 30220006, 2018). "However, in our study, the risk of hypoglycemia increased when SGLT2 inhibitors were sequentially added to pre-existing DPP4 inhibitors, which was probably due to a study that permitted insulin and/or sulfonylureas as background anti-diabetes therapy." (PMID 29535389, 2018). "Δ6-desaturase is activated by insulin, whereas diabetics have reduced Δ6-desaturase activity." (PMID 30347877, 2018). "Abnormal insulin secretion, rather than insulin resistance, is a major cause for the development of diabetes in GK rats." (PMID 30258609, 2018). "If stabilization of IDE substrates by an N-terminal Pro-1 is possible in principle, this might also be of interest to increase the half-life of insulin preparations and thereby to enhance bioavailability of administered insulin in diabetes patients." (PMID 30545091, 2018). "Insulin treatment could attenuate the stimulating effect of diabetes on colon ECM deposition and TGFβ/Smad signaling." (PMID 29930382, 2018). "Pancreas development is normal and diabetes is due to impaired insulin secretion." (PMID 28943513, 2018). "Blood glucose and insulin levels decreased in Klotho gene knockout mice, although insulin sensitivity increased, suggesting that Klotho is closely related to the incidence of diabetes." (PMID 29900135, 2018). "Lack of UCN3 has been linked to excessive insulin release, contributing to the pathophysiology of diabetes." (PMID 30400826, 2018). "Of patients with IPMN, 10–45% have diabetes and in the case of diabetes, the risk of detecting IPMN is higher (OR 1.79; 95% CI 1.08–2.98), especially in the case of insulin-use (OR 6.03, 95% CI 1.74–20.84)." (PMID 30196428, 2018). "A return to euglycemia and discharge following a short observation period are common place for individuals taking short-acting insulin agents; however, time needed for observation for individuals taking diabetes medications other than short acting insulin is more controversial." (PMID 29799604, 2018). "In contrast, insulin release from an unregulated subcutaneous depot in type 1 diabetes and/or the continued action of sulfonylureas in a non-glucose dependent manner in type 2 diabetes means that systemic insulin levels remain relatively high during hypoglycaemia in diabetes." (PMID 29417183, 2018).
diabetes (continued). "Using subgroup analysis stratified by age, sex, duration of diabetes, duration of insulin treatment, and complications, still more outpatients in every subgroup treated with premixed insulin achieved the target HbA1c (HbA1c < 7%) than those receiving basal insulin." (PMID 30420835, 2018). "In turn, glycolysis could drive obesity and diabetes, by driving persistent elevation of insulin secretion leading to obesity and pancreatic burn-out." (PMID 29892261, 2018). "Diabetes mellitus (DM) is a metabolic disorder characterized by chronic hyperglycemia with abnormal carbohydrate, fat, and protein metabolism due to defects in insulin secretion, insulin action, or both." (PMID 30271452, 2018). "We generally expect that insulin sensitivity ought to be lowered in diabetes." (PMID 29915545, 2018). "In the present study, an association between fasting plasma mannose levels and insulin sensitivity independent of BMI was observed in individuals with diabetes and not in individuals without diabetes." (PMID 30534205, 2018). "Despite considerable advances in pharmacotherapy, insulin delivery systems, and self-monitoring technologies in the last decades, a large percentage of adults with diabetes remain unsuccessful in achieving optimal glucose control, reflected by not reaching their HbA1c goals." (PMID 29707584, 2018). "Strategies to manage diabetes include insulin replacement and aerobic exercise regimes." (PMID 30425651, 2018). "Family history of diabetes and insulin treatment of GDM may be predictors of postpartum hyperglycemia." (PMID 30186874, 2018). "Diabetes may outbreak because of low insulin secretion by Islets of Langerhans β-cells, insulin resistance or both of them." (PMID 30595825, 2018). "However, she did require strict glucose control for previously diagnosed diabetes mellitus with insulin titrated to 52 units daily towards the end of gestation (HbA1c 5.20–5.50%)." (PMID 30526530, 2018). "However, mortality varied across all studies in terms of the cut-off point for BG, diabetes status, ICU type, underlying disease, type of insulin control, and mortality measurement time-point." (PMID 29624594, 2018). "Value of the data•Many type 2 diabetes mellitus (T2DM) patients are reluctant to start insulin therapy and may delay beginning it for significant periods of time." (PMID 29904712, 2018). "This ability may be useful for some of those with diabetes, a natural method to help lower blood sugar, take less insulin, or in some instances stop taking insulin altogether." (PMID 30271430, 2018). "A disruption in the governance of the glucose-insulin system can lead to variable degrees of altered glucose regulation, which may ultimately result in overt diabetes mellitus." (PMID 29420588, 2018). "For VD, low insulin predicted dementia independently of diabetes comorbidity." (PMID 29997193, 2018). "Diabetes is a chronic disease marked by the presence of hyperglycemia that occurs when the pancreas cannot produce enough insulin, or the body cannot effectively use the insulin that is produced." (PMID 29710777, 2018). "Adolescents with T1DM have significant difficulty achieving optimal glycemic control due to challenges in shifting and evolving social priorities that can interfere with medication adherence, increasing insulin requirements characteristic of puberty, diabetes-related distress, and family conflict." (PMID 33052121, 2018). "Markers of glucose metabolism disorders (e.g., insulin and insulin resistance-HOMA-IR) are commonly associated with the microbial genotype, suggesting that people with fewer genotypes are predisposed to metabolic disorders and secondarily to diabetes." (PMID 30539026, 2018). "It is believed that EA may be used to prevent diabetes and metabolic syndrome since it can ameliorate insulin sensitivity." (PMID 30524482, 2018).
diabetes (continued). "Basal-bolus insulin therapy provides a physiological approach to the treatment of patients with diabetes inasmuch as it covers both basal (i.e., overnight fasting and between-meals) and prandial (i.e., glucose excursions above basal levels at mealtimes) insulin needs." (PMID 30918874, 2018). "It is postulated that in the development of T2DM in youth, an early defect in first-phase insulin response, is followed by defects in second-phase response with development of overt diabetes, and these deteriorations occur in the context of a decline in insulin sensitivity." (PMID 29471797, 2018). "The association with low fasting insulin was also seen when dementia without diabetes comorbidity was the outcome of interest, considering dementia with diabetes mellitus as a competing event." (PMID 29997193, 2018). "Furthermore, insulin therapy cannot significantly improve diabetes-related complications in patients with advanced diabetes mellitus." (PMID 30053902, 2018). "For example, the dysregulation of miR-29 influenced the glucose and lipid metabolism in skeletal muscle in diabetes, and the TF FoxO1 could regulate hepatic insulin sensitivity and lipid metabolism." (PMID 30140229, 2018). "Diabetes mellitus, which is commonly referred to as diabetes, is a chronic metabolic disorder in which high blood glucose levels are present in the body over a prolonged period due to defects in the production and/or function of insulin." (PMID 29849917, 2018). "For the 12-month period of evaluation between November 2010 and October 2011, internal medicine residents ordered BBI for 41.9% of diabetes patients, compared to 16.7% of patients in the 12 months before the pocket insulin dosing guide was introduced (P < 0.01)." (PMID 30155381, 2018). "Areas beyond insulin therapy, but within the context of improving diabetes care, that have been included in the guidelines are lifestyle modifications and target values for glucose control based on the glycemic hexads (HbA1c, FPG, PPG, hypoglycemia, nocturnal hypoglycemia, and glycemic variability)." (PMID 29508275, 2018). "Regarding diabetes treatment previous to stroke, 186 (54.9%) patients were taking oral antidiabetics [88/162 women (54.3%), and 98/177 (55.4%) men, p = 0.847; and 75 (22.1%) were under insulin treatment, 39/162 women (24.1%) and 36/177 men (20.3%), p = 0.408]." (PMID 29706931, 2018). "One study recruited individuals who managed their type 2 diabetes mellitus through diet only, and two studies used eligibility criteria that restricted the use of insulin but allowed hypoglycaemic drugs and dietary interventions, but provided no specific details." (PMID 29754286, 2018). "Furthermore, the increased expression of Pepck and Pdk4 genes (CCGs in the kidneys and liver) with higher levels of blood glucose and serum insulin exacerbated the processes of insulin resistance and diabetes in high-fat-diet-induced obesity." (PMID 29385702, 2018). "This is one of the first demonstrations that the system responsible for clearing brain extracellular solutes is affected by diabetes and might explain how insulin resistance may contribute to the initiation and progress of AD." (PMID 29743868, 2018). "When insulin function becomes impaired as a result of conditions such as diabetes, insulin resistance may develop." (PMID 29462993, 2018). "Among the identified significant SNPs by joint testing, there were 79 novel genome-wide significant SNPs that have not been reported as significantly associated with diabetes-related fasting glucose and insulin levels before." (PMID 29743933, 2018). "Diabetes is caused by a lack of insulin secretion or insulin resistance and low utilization of sugar, which then can lead to brain, heart, kidney, heart failure, acute myocardial infarction and other organ complications that can severely harm human health." (PMID 30131712, 2018). "First, we investigated the influence of exogenous insulin use in diabetes patients." (PMID 30092829, 2018).
diabetes (continued). "Certainly, above elements of purinergic signaling constitute novel mechanisms for regulation of β-cell mass and enhancement of insulin release and thus could be important targets for diabetes therapy." (PMID 29895988, 2018). "The earliest publication in a population without diabetes or renal disease comes from Japan; a significant positive association was seen between insulin levels and serum creatinine." (PMID 29855339, 2018). "However, the hinder of cell transplantation for diabetes treatment is insufficient sources of insulin-producing cells." (PMID 29868580, 2018). "In severe forms of diabetes, the current treatment of insulin administration is inadequate, and pancreatic islet (PI) transplantation is considered as a promising therapeutic alternative, as 20% of patients were insulin independent five years after PI transplantation." (PMID 29534555, 2018). "Diabetes is a chronic disease caused by the absence of insulin secretion (T1D) or defective insulin secretion and action (T2D)." (PMID 29986473, 2018). "Blood glucose management by insulin also inhibited diabetes‐induced ROS overproduction." (PMID 29659121, 2018). "Because of the small sample size in this study, we were unable to conclude that other variables, including prepregnancy obesity and insulin therapy during pregnancy as well as fasting PG during the diagnostic OGTT for GDM, were not significant predictors for the development of postpartum diabetes." (PMID 29310607, 2018). "Twin studies can estimate the multifactorial genetic involvement in T2D more precisely and have reported high degree of heritability of diabetes-related conditions such as disorders of first phase insulin response and basal and insulin-stimulated glucose uptake." (PMID 29736170, 2018). "The drugs most commonly used for diabetes were insulin, metformin, and drugs to treat co-morbidity." (PMID 28870280, 2018). "Diabetes results from defects in insulin and glucose control." (PMID 30539026, 2018). "Pre-diabetes and diabetes in patients with thalassemia has demonstrated that both decreased insulin secretion and resistance may be involved." (PMID 29899542, 2018). "In addition to the inherent limitations due to its retrospective design, the main limitation of our study is in the failure of our patients with diabetes on glucocorticoid treatment to achieve adequate glycemic control on the basal-bolus insulin protocol." (PMID 30373567, 2018). "Alström syndrome (ALMS) is a very rare autosomal recessive monogenic disorder caused by a mutation in the ALMS1 gene and characterised by childhood onset obesity, dyslipidaemia, advanced non-alcoholic fatty liver disease, diabetes and extreme insulin resistance." (PMID 30477455, 2018). "Regarding incident diabetes mellitus, the largest risk was observed for high vs medium values of fasting insulin, and no risk at all was seen for low insulin." (PMID 29997193, 2018). "Education and correct instruction of clinicians and patients according to available information about such factors are essential in order to achieve the best glycaemic result, improve the long-term prognosis, and increase quality of life in people with diabetes that use insulin." (PMID 30116732, 2018). "Pharmacological therapies like metformin (lowers blood glucose and insulin levels), sulfonylurea (promotes secretion of insulin from the pancreas) and insulin analogues (glargine) are available to treat diabetes; however these treatments often fail after prolonged usage." (PMID 30567565, 2018). "Insulin is the most effective drug for the treatment of diabetes." (PMID 30918874, 2018). "In recent years, several peptides from frog skin, firstly identified by their antimicrobial or immunomodulatory activities, were proven to have the function of stimulating insulin release in vitro and in vivo, thus showing the potential of development into agents against diabetes." (PMID 30301245, 2018).
diabetes (continued). "Use of diabetes drugs such as sulfonylurea and metformin seems directly influence ATP-sensitive k+ channels for enhancing membrane depolarization of pancreatic beta cells and stimulating exocytosis of insulin granules." (PMID 29961900, 2018). "The relation between increased CD44v expression and reduced insulin secretion in three different types of diabetic model mice, with each model reflecting a different type of islet dysfunction, implicates CD44v in the pathophysiology of diabetes." (PMID 29434323, 2018). "Overall, the present study demonstrated that the combination of ketogenic diet and a moderate-intensity aerobic exercise intervention improved insulin sensitivity in diabetic mice, while avoiding hepatic steatosis, which provided a novel strategy in the combat of diabetes." (PMID 29743883, 2018). "Interestingly, HOMA-β levels tend to be lower in individuals with a family history of diabetes due to lower levels of insulin secretion as a result of impaired β-cell function." (PMID 30473679, 2018). "SMBG in diabetes management helps in making treatment decisions and correcting insulin dose." (PMID 29508275, 2018). "The model was adjusted by age, sex, smoking, drinking, obesity, past history of impaired glycometabolism or diabetes, including current use of insulin or glucose-lowering agents, past history of dyslipidemia, including current use of lipid lowering agents, or past history of hepatic impairment." (PMID 29538435, 2018). "The relationship between severe hypoglycaemia and all-cause mortality was maintained after adjustment for the following baseline characteristics: age, sex, HbA1c, BMI, diabetes duration, insulin regimen, hepatic impairment, renal status and cardiovascular risk group inclusion criteria." (PMID 28913543, 2018). "While initially T2DM may be protective for fracture, possibly due to hyperinsulinemia through insulin’s homology with IGF-1 causing increased bone strength, longer exposure of diabetes is associated with increased fracture risk." (PMID 29721333, 2018). "The discovery of insulin has been a milestone and has truly revolutionized both the therapy and the prognosis of the diabetes, one of the diseases most studied in the history of medicine, whose first mentions trace back to a collection of ancient Egyptian, Indian and Chinese textbooks." (PMID 30405529, 2018). "Moreover, insulin therapy cannot prevent from major diabetes complications which can result in permanent disabilities or even death as a result of hypoglycemia." (PMID 29373983, 2018). "However, this would only have confounded the analyses if diabetes status or insulin use would have been differentially distributed between laboratories or years of diagnosis, and this was not the case." (PMID 29486734, 2018). "In another study evaluating the trajectory of metabolic changes, a linear increase in fasting glucose started 3 years before diagnosis of diabetes, whereas insulin sensitivity (HOMA) decreased during the 5 years before and ß-cell function increased 4 years before diagnosis." (PMID 30271382, 2018). "Overall, 127 MB of 190 MB GK PASS regions (67%) overlapped with 101 of 109 candidate QTLs indicating most of the PASS regions were involved in GK or diabetes physiological phenotypes such as blood/plasma glucose level, body weight, serum insulin level, and pancreatic islet damage." (PMID 30687391, 2018). "Lastly, considering the epidemiologic feasibility, some other biochemical indexes that are reported to correlate with the presence of diabetes such as plasma insulin, estimated insulin resistance, plasma ghrelin, adiponectin, leptin and cytokines were not collected in our cross-sectional design." (PMID 30314516, 2018). "After in vitro characterization and in vivo optimization with the green fluorescent protein (GFP) reporter gene, we show that CS‐g‐bPEI/pDNA NPs can effectively deliver a human insulin plasmid to reduce blood glucose levels in mice with streptozotocin (STZ)‐induced diabetes." (PMID 30128227, 2018).